IL33 (interleukin 33)
Diseases named in the same sentence as IL33 in open-access papers (continued):
Sharing a sentence is not in itself a finding about the gene and the disease.
inflammation (continued). "In animal experiments, infusion of 1,4NQ-BC into mice triggered lung inflammation and stimulated IL-33 secretion from lung tissues, primarily from macrophages." (PMID 39301028, 2024). "To validate this result in vivo, we assessed the expression of CD47 proteins on ILC2s in a mouse model of IL33-mediated airway inflammation." (PMID 39160226, 2024). "In SpA, circulating levels of IL-33 were increased and in IBD, tissue expression of IL-33 was enhanced and increased in cases of intestinal inflammation." (PMID 37280714, 2023). "The roles of PGE2 receptors EP2 and EP4 on ILC2‐mediated lung inflammation were investigated using genetically modified mouse lines and pharmacological approaches in IL‐33‐induced lung allergy model." (PMID 36181709, 2023). "Tissues contribute significantly to IL-33 expression, and its levels can rise during inflammation, with tissue-derived IL-33 being crucial for certain inflammatory responses like Th2-induced airway inflammation." (PMID 38137450, 2023). "The full-length IL-33 can interact with NF-κB, a critical regulator of immune and inflammatory responses such as chronic intestinal inflammation and AD." (PMID 36982304, 2023). "T cell–intrinsic TRAF4 is critical for the expansion of ST2+ mTh2 cells in IL-33–induced airway inflammation." (PMID 37607012, 2023). "AD skin lesions are enriched for skin-resident ILC2s, which are activated by TSLP or IL-33, promoting type 2 inflammation." (PMID 35359972, 2022). "IL-33 thereby induces the expression of Acyl-CoA synthetase (Acsbg1), an enzyme important for fatty acid oxidation in the mitochondria, which further promotes the resolution of IL-33-induced airway inflammation." (PMID 35936011, 2022). "Rapamycin treatment decreased IL-33-induced eosinophilic airway inflammation, possibly by inhibiting IL-5-producing bone marrow ILC2s." (PMID 35720347, 2022). "Full length (fl)‐IL‐33, as a transcription factor mainly in the cell nucleus, mediated non‐atopic lung inflammation and fibrosis by modulating expressions of several pro‐fibrotic mediators, including transforming growth factor (TGF)‐b1." (PMID 36082495, 2022). "CGRP released from lung neuroendocrine cells also promoted ILC2 activation in combination with IL-33 or IL-25 in lung inflammation induced by ovalbumin (OVA) challenge." (PMID 34177944, 2021). "In various models of airway inflammation in mice, IL-33, IL-25 and/or TSLP showed increased expression in the lungs after inhalation of antigens." (PMID 33723298, 2021). "IL-33 is a member of the IL-1 family of cytokines, is a potent activator of ILC2s, and primarily promotes steroid-resistant eosinophilic inflammation." (PMID 35387021, 2021). "The in vivo data showed that PM aggravated HDM-induced airway inflammation, and IL-33 neutralizing antibody exerted a protective role." (PMID 34254951, 2021). "Although IL-33 has adverse functions, like as impairments in established immunologic tolerance in the lung, even exacerbates sterile liver inflammation." (PMID 33936076, 2021). "Similar to the findings in helminthic lung infections, ST2+ nILC2s (called ILC217s) are defined in the lung inflammation induced by papain or IL-33, which possesses some characteristics of ILC3s, for example, AhR expression and IL-17 production." (PMID 33718260, 2021). "This verifies that the IL-33 antibody exerted a protective role on PM-aggravated HDM-induced airway inflammation." (PMID 34254951, 2021). "To address this issue, we employed a mouse model of acute lung inflammation induced by a recombinant murine protein IL-33, which is known to robustly activate ILC2 cell–mediated lung inflammation." (PMID 33400692, 2021). "These epithelial cytokines are believed to play important roles in mediating immune response in lung, and intranasal treatment of mice with IL-33 or IL-25, has been shown to induce pulmonary inflammation." (PMID 34970267, 2021).
inflammation (continued). "This idea would be consistent with previous studies in which Treg-derived IL-10 was able to suppress ILC2-driven papain-induced airway inflammation via an IL-33/mast cell axis." (PMID 32931477, 2020). "To address this issue, we used the recombinant murine protein IL-33 to elicit an acute lung inflammation." (PMID 32730309, 2020). "IL-33 from monocytes recruited to the lung contributes to the pathogenesis of HDM-induced airway inflammation." (PMID 31820024, 2020). "In line with this, experimental in vitro and in vivo blockade of ICOS signaling markedly inhibited the pro-inflammatory properties of human ILC2s, resulting in reduced airway inflammation in a humanized mouse model of IL-33-induced airway hyperreactivity." (PMID 32655549, 2020). "Studies of allergen-induced airway inflammation using IL-33/ST2 knockout mice or neutralizing antibodies against IL-33/ST2 reported decreased type 2 inflammation and lower eosinophilic inflammation as a consequence." (PMID 32466530, 2020). "Using human TNF-α transgenic mice, which develop spontaneous joint inflammation and cartilage destruction, IL-33 inhibited TNF-α-mediated bone loss via the IL-33/ST2 axis." (PMID 32046264, 2020). "We have reported that monocytes recruited into the lungs represent cell sources of IL-33 in HDM-induced airway inflammation in mice." (PMID 31820024, 2020). "Previously, IL-33-neutralizing antibody was found to suppress epithelial damage and pulmonary inflammation, benefiting lung development in BPD-like mice." (PMID 32377396, 2020). "Several recent studies have demonstrated that ILC2 is a major inducer of eosinophilic airway inflammation when IL-33 is intratracheally administered." (PMID 31167385, 2019). "For the investigation of the expression of downstream cytokines related to the IL-33/ST2 receptor signaling axis, IL-13 is mainly secreted after IL-33 stimulation and can induce epithelial injury and biliary inflammation." (PMID 31632941, 2019). "Using mice model, butyrate has recently been found to inhibit proliferation and function of ILC2s by inhibiting intracellular GATA3 activity to suppress IL-33-mediated airway hyperresponsiveness and airway inflammation." (PMID 30886621, 2019). "Taken together, IL-33 displays a central role in LPS-induced lung inflammation/injury and MMP2/9 secretion." (PMID 30410547, 2018). "We will further provide an overview on the immunoregulatory role of a special type of DAMP or alarmin in sterile liver inflammation-the cytokine interleukin (IL)-33." (PMID 30213101, 2018). "Despite the weak evidence for an interaction of the NLRP3 inflammasome and IL-33 pathway in sterile liver inflammation, a NLRP3-IL-33 axis has been shown in other diseases." (PMID 30213101, 2018). "Upon IL-33-induced airway inflammation, PIN1 is activated for binding with and isomerization of IRAK-M, resulting in IRAK-M nuclear translocation and induction of selected proinflammatory genes in dendritic cells." (PMID 29686383, 2018). "Published studies have demonstrated that the TH2 production of the cytokine IL-13, in response to stimulation with IL-33, can promote the hyperplasia of epithelial cells in the context of airway inflammation." (PMID 28931041, 2017). "Accordingly, intranasal administration of IL-25 or IL-33 induces eosinophilic airway inflammation and expansion of ILC2s, independently of B or T cells." (PMID 29250067, 2017). "While activation of the innate immune system in part through ST2/IL-33 signaling establishes airway inflammation, ST2+ T cells maintain this inflammation." (PMID 28484466, 2017). "We showed that mice exposed to antigen through the skin, in the presence of IL-33, developed antigen-specific airway inflammation when later challenged in the lung." (PMID 28490737, 2017). "Using a house dust mite (HDM)-induced airway inflammation mouse model, we demonstrated, in vivo and in vitro, the possibility that IL-33 from monocytes recruited to the lung played an important role." (PMID 27310495, 2016).
inflammation (continued). "The aim of this study was to clarify the role of IL-33 production by monocytes in airway inflammation." (PMID 27310495, 2016). "Alveolar macrophages are polarised towards an alternatively activated phenotype in response to IL-33- and ST2-deficient mice have attenuated ovalbumin-induced airway inflammation associated with a decrease in AAM differentiation." (PMID 27001429, 2016). "We also found some differences between EC sensitized ST2-/- mice and EC sensitized IL-33-/- mice in development of airway inflammation after OVA challenge." (PMID 26230091, 2015). "We evaluated the effects of vaccination against IL-33 in a mouse model of airway inflammation induced by house dust mite (HDM) allergen." (PMID 26214807, 2015). "Our present findings demonstrate that vaccination against IL-33 elicits high titers of specific anti-IL-33 antibodies that markedly attenuate the development of airway inflammation and AHR, particularly within distal airways, in mice sensitized to HDM." (PMID 26214807, 2015). "To evaluate the efficacy of our IL-33 vaccine we employed an HDM-induced model of airway inflammation in mice with a long (42-day) sensitization and challenging period and a moderate dose of allergen (25 μg)." (PMID 26214807, 2015). "The direct administration of IL-33 to mouse lung induces IL-5-producing T cells, thus exacerbating allergen-induced airway inflammation." (PMID 24586149, 2014). "Accumulating evidence shows that IL-33 has an important role during the development or exacerbation of airway inflammation." (PMID 24586149, 2014). "The most important and unique aspect of the present report is the new evidence presented that the novel cytokine IL-33 exacerbates acute pancreatic inflammation." (PMID 23418608, 2013). "The dichotomous role of the IL-33/IL1RL1 axis within the context of chronic intestinal inflammation has been previously proposed and may explain the results obtained within the present study regarding the association of the rs3939286 polymorphism of IL-33 with IBD and with specific UC phenotypes." (PMID 23634226, 2013). "Intranasal administration of IL-33 to wild-type mice induced airway inflammation, whereas adoptive transfer of wild-type ILCs to IL-33 receptor–deficient (St2−/−) mice recapitulated this response." (PMID 22738676, 2012). "Having determined an important role for mTOR in the induction of TH2 cell cytokine production, we sought to examine the function of this signaling pathway in the induction of airway inflammation by IL-33 in vivo." (PMID 22738676, 2012). "A similar study by Louten and colleagues has also shown that endogenous IL-33 contributes to airway inflammation and peripheral antigen-specific responses in ovalbumin-induced acute allergic lung inflammation using IL-33-/- mice." (PMID 21871091, 2011). "Furthermore, two treatment models using SLPI KO mice, administration of a serine protease inhibitor, bovine pancreatic trypsin inhibitor, or anti-IL-33 antibody, attenuated Th2 airway inflammation." (PMID 40546642, 2025). "Finally, we validated these findings in vivo using a mouse model of IL33-mediated airway inflammation." (PMID 40627441, 2025). "Recent advancements in COPD treatment have introduced biologic agents such as Dupilumab (anti-IL-4Rα monoclonal antibody), Ensifentrine (a dual PDE3/4 inhibitor), and anti-IL-33 therapies, which have shown promise in controlling airway inflammation, particularly in patients with type 2 inflammation." (PMID 40333888, 2025). "On the other hand, other reports have revealed that the Il5hi subpopulation of ILC2s expresses Calca-encoding CGRP in addition to CGRP receptors, and CGRP administration suppressed IL-33 production or papain-induced pulmonary eosinophilic inflammation and worm expulsion in a murine model." (PMID 37371472, 2023).
inflammation (continued). "The authors concluded that up-regulated IL-33 levels may facilitate lung inflammation by promoting the production of a range of innate pro-inflammatory cytokines, including TNF-α, IL-1β, IL-6, IL-12, IL-23." (PMID 36875710, 2023). "Early life hyperoxia exposure enhances innate lymphoid cell (ILC2) function by increasing the expression of IL-33, and ILC2s produce type 2 cytokines such as IL-5, IL-13, and mediators involved in tissue repair, leading to eosinophilic airway inflammation and airway remodeling." (PMID 37485534, 2023). "Interestingly, inhibition of glycolysis significantly decreased inflammatory cytokine levels (IL-25 and IL-33), suggesting glycolysis to be involved in asthmatic lung inflammation." (PMID 36441389, 2023). "Furthermore, we demonstrated that the adaptive immune system was dispensable during both papain challenge and IL-33-induced eosinophilic airway inflammation, exhibiting ILC2s as potent sources of type 2 cytokines driving the eosinophilic inflammation." (PMID 35720347, 2022). "Thus, we believe betuletol can improve the symptoms of eosinophilic inflammation more specifically by suppressing IL-33 gene expression and thus decreasing the number of eosinophils." (PMID 36080225, 2022). "To evaluate this, we investigated the effects of FK506 on IL-33-induced airway inflammation." (PMID 36439133, 2022). "In addition, the adoptive transfer of IL-33-treated DCs to naïve mice enhances lung airway inflammation." (PMID 36142703, 2022). "In the present study, however, IL-33 deficiency did not affect PPE-induced neutrophilic airway inflammation." (PMID 33992109, 2021). "Treatment with anti-IL-33 antibody has been reported to inhibit CS-induced airway inflammation." (PMID 33992109, 2021). "In addition, intestinal dysbiosis plays pathological roles in the development of chronic pancreatic inflammation as dysbiosis mediates the activation of pDCs producing IFN-α and IL-33, thereby causing experimental AIP." (PMID 33833754, 2021). "Interestingly, acute models of liver inflammation observed a protective effect of IL-33 on hepatocytes and liver function, data suggests that IL-33 works as a protective mechanism in acute liver damage but stimulates tissue fibrosis in chronic injuries." (PMID 34489979, 2021). "Collectively, we highlight that c-Rel is important for ILC2-dependent lung inflammation in response to papain and IL-33, with this finding confirming and extending previously published work on the role of c-Rel in promoting ovalbumin-alum induced airway inflammation." (PMID 34194431, 2021). "Increased expressions of IL-17RB and ST2 on mDCs are associated with enhanced local Th2 inflammation in NP, suggesting that mDCs might play a role in IL-25- and IL-33-induced type 2 responses and eosinophilic inflammation in NP." (PMID 30519393, 2018). "Additionally, T cell-derived IL-21 promotes type 2 immunity to HDM and blockade of CD28 signaling during HDM exposure represses airway hyperreactivity and lung inflammation, further supporting that both IL-33 and T cells are necessary for full ILC2 responses." (PMID 29250067, 2017). "Separately, IL-33 or OVA administration induced lung inflammation." (PMID 28652606, 2017). "Importantly, all pathological changes were attenuated by a neutralising anti-IL-33 antibody suggesting that IL-33 plays a critical role in cigarette-smoke-mediated airway inflammation." (PMID 27001429, 2016). "IL-33 from monocytes recruited to the lung may contribute to the pathogenesis of HDM-induced airway inflammation." (PMID 27310495, 2016). "Since long-term exposure of mice to HDM, but not OVA, results in chronic airway inflammation associated with tissue remodeling, these observations suggest that IL-25, IL-33 and TSLP play different pathogenic roles in the acute and chronic phases of airway inflammation." (PMID 24205109, 2013).
inflammation (continued). "The purpose of this review is to explore the role of IL-33 in modulating epithelial repair, mucosal healing, and fibrosis in the GI tract during normal gut homeostasis and in the setting of chronic intestinal inflammation." (PMID 23062310, 2012). "We show that blocking the IL-33 pathway may mitigate glomerular endothelial inflammation in DKD." (PMID 38899206, 2024). "Expansion of ILC2s and activation by IL-33 from damaged parenchymal cells results in IL-13 production driving fibrotic gene expression in hepatic stellate cells in fibrosis models, or IL-5 production with resultant hepatic inflammation and eosinophilia in immune-mediated hepatitis models." (PMID 35359972, 2022). "Using a mouse model of IL-33-induced lung inflammation, the pathophysiological in vivo relevance of this interaction could be strengthened: blocking the CD11a subunit of the ligand LFA-1 resulted in decreased signs of lung inflammation in immunodeficient Rag1−/− mice." (PMID 32655549, 2020). "Furthermore, the IL-17RB and ST2 expressions on mDCs were also correlated with the IL-5 mRNA level and eosinophil numbers in NP tissues, suggesting that mDCs might play a role in IL-25- and IL-33-induced type 2 responses and eosinophilic inflammation in NP." (PMID 30519393, 2018). "Loss of both IL-4 and IL-5 during OVA-induced airway inflammation did not abolish airway hyperreactivity, which was abolished only after anti-CD4 treatment, suggesting that ST2/IL-33 signaling in CD4 T cells may be critical for efficient antigen-induced airway inflammation." (PMID 28484466, 2017). "A recent study revealed that a TLR7 agonist stimulated IL-33-induced interstitial macrophages to produce IL-27, suppressing ILC2-driven airway inflammation." (PMID 37371472, 2023). "In an animal model of induced intestinal inflammation, exogenous AREG treatment ameliorated disease severity and promoted favorable tissue remodeling through induction of IL-33-activated ILC2 cells." (PMID 36797300, 2023). "The result showed that PM exposure resulted in the pulmonary accumulation of IL-33 and IL-25 in the HDM-induced airway inflammation (p < 0.001, p < 0.01)." (PMID 34254951, 2021). "Recent studies have highlighted an important role of epithelial cytokines, including IL-25, IL-33 and TSLP, in lung inflammation." (PMID 34970267, 2021). "Initially, we utilized an IL-33-based model of AHR because both IL-33 and IL-25 have been previously shown to induce ILC2-mediated AHR and lung inflammation, although IL-33 is more potent than IL-2522." (PMID 33953190, 2021). "Firstly, by using recombinant IL-33 to induce lung inflammation in vivo, we explored the effects of PNU-282987 and GTS-21 on IL-33–mediated airway inflammation." (PMID 33597946, 2020). "In an allergic airway disease model, deletion of IRF4 expression in CD11c+ cells attenuated Th2-type lung inflammation, and IRF4 was found to directly modulate IL-10 and IL-33 production by DCs, promoting Th2 differentiation and inflammation." (PMID 29343807, 2018). "Here the authors show, using biochemical, structural and patient data, that upon IL-33 or allergic challenge, the isomerase Pin1 modifies IRAK-M to control the production of pro-inflammatory cytokines in the setting of airway inflammation." (PMID 29686383, 2018). "Increased expression of IL-33 is detected in SAMP mice, a spontaneous model of chronic intestinal inflammation characterized by a mixed Th1/Th2 immune phenotype." (PMID 28710436, 2017). "Bleomycin enhanced the production of the mature form of IL-33 in lung tissue, while deletion of the IL-33 receptor (IL-1 receptor-like 1; ST2) attenuated the bleomycin-induced lung inflammation and fibrosis." (PMID 28202030, 2017). "When using GATIR mice in an acute HDM-driven airway inflammation model, we detected the induction of a much more heterogeneous ILC2 population in BAL fluid, lungs, and draining lymph nodes than upon robust IL-33-induced ILC2 activation." (PMID 29250067, 2017).